STAT3 (signal transducer and activator of transcription 3)
Diseases named in the same sentence as STAT3 in open-access papers (continued):
Sharing a sentence is not in itself a finding about the gene and the disease.
tumor (continued). "Consequently, the activation of cancer-related signaling pathways such as AKT, ERK, AP-1, STAT3, and NF-kB was inhibited, leading to a blockade in tumor proliferation and invasion capabilities." (PMID 38217031, 2024). "The findings verify the strong relationship between STAT3 and tumor cell death." (PMID 39588118, 2024). "Thus, STAT3 imaging probes can visualize cancer pathology and provide essential indicators of tumor progression." (PMID 38834900, 2024). "Of note, pharmaceutical inhibition of FXR significantly suppresses IL-6/IL-6ST/p-STAT3 signaling and reduces metastatic tumor burden in mouse NSCLC metastasis models, suggesting a potential therapeutic approach for this subgroup (characterized by FXRhigh) of metastatic NSCLC patients." (PMID 38360812, 2024). "Moreover, STAT3 signaling was inhibited when various tumor cell lines were received treatment of mTOR inhibitor rapamycin, which supports our observation that STAT3 phosphorylation was inhibited by the combination of PQR309 and gemcitabine." (PMID 38555280, 2024). "Activated STAT3 is a key dedicator to tumor survival, proliferation, invasion and metastasis." (PMID 38385088, 2024). "Additionally, AKR1C3 promotes tumor proliferation and invasion through the IL6/STAT3 pathway, as evidenced by gain- and loss-of-function experiments." (PMID 38523637, 2024). "Moreover, IL-10 recruited Tregs44,45, and the inhibition of STAT3 and NF-κB reduced the tumor secretion of IL-1044,46." (PMID 39085255, 2024). "Moreover, the level of STAT3 phosphorylation is closely related to tumor grading, with significant differences observed between low-grade and high-grade tumors." (PMID 39563863, 2024). "Hence, the enrichment of STAT3 signature genes was likely attributed to tumor-adjacent astrocytes and infiltrated immune cells." (PMID 38386085, 2024). "Moreover, active STAT3 can promote tumor metastasis in a variety of human cancers via the upregulation of VEGF and other angiogenic factors such as angiopoietin, chemokines mediating tumor invasion, and matrix metallopeptidase-9." (PMID 38256080, 2024). "Furthermore, the STAT3 pathway stimulates specific transcription factors in tumor cells that support the EMT process, resistance to apoptosis, invasion, proliferation, and immunosuppression." (PMID 39061137, 2024). "Additionally, these metabolites play a pivotal role in the regulation of several tumor-associated signaling pathways, including the PI3K/Akt, MAPK/ERK, JAK/STAT3, and Wnt/β-catenin pathways." (PMID 39346560, 2024). "It is secreted by TAMs and promotes tumor-cell proliferation via the JAK2/STAT3 signaling pathway." (PMID 39199574, 2024). "Accordingly, this protein has been largely considered as a potential therapeutic target in different tumor types, leading to the development of a new class of antineoplastic drugs, STAT3 inhibitors, classified as indirect or direct based on their mechanism of action." (PMID 38781107, 2024). "LINC01106 Knockdown reduces p-STAT3 and Bcl-2, inhibiting tumor growth." (PMID 38185635, 2024). "Our study unveiled a mechanism about SRI as a tumor promotor, interacting with STAT3, inhibited mitochondrial apoptosis by the NF-κB pathway in HCC, which suggests that SRI maybe considered as a promising therapeutic target for HCC." (PMID 39000312, 2024). "Despite their crucial role in regulating tumor cell proliferation, differentiation, and apoptosis, the precise mechanisms and long-term consequences of STAT3 and STAT5 remain relatively unknown." (PMID 38840908, 2024). "Furthermore, post-irradiation activation of STAT3 contributes to immune suppression and radiation resistance in various tumor models." (PMID 39285178, 2024). "In addition, STAT3 inhibitor napabucasin was employed to reduce the stemness of tumor cells, thus allowing CTLs to eliminate tumor efficiently." (PMID 38564766, 2024).
tumor (continued). "This can be attributed to the low expression of CTLA-4 by IL-17-producing Tregs, which leads to Forkhead box O 3 (FoxO3) inactivation in DCs and the activation of the IL-6 production-STAT3 signaling pathway in tumor cells, ultimately promoting their proliferation." (PMID 38317142, 2024). "Furthermore, the identification of Wnt-regulated long noncoding RNAs (lncRNAs), such as CCAT5 and CCAT2, has revealed their critical roles in regulating STAT3 activity and promoting tumor development." (PMID 39767561, 2024). "Moreover, TRIB3 has been found to interact with STAT3, mediating angiogenesis and promoting tumor metastasis." (PMID 39881875, 2024). "In addition, it has been demonstrated that the over-activation of JAK2/STAT3 is implicated in AML tumorigenesis, and targeting this pathway enhances the anti-tumor effects of arsenic trioxide in AML cells." (PMID 39704857, 2024). "Targeting B7H4 could also decrease xenograft tumour weight and volume in vivo, but again, these effects were reversed upon PD-1/STAT3 induction using Colivelin." (PMID 39061159, 2024). "In addition, enhanced STAT3 activity plays a central role in tumor progression, both through the way tumor cells are intrinsic and through its ability to regulate the environmental activity of surrounding cells." (PMID 38320998, 2024). "It is plausible that curcumin exerts anti-cancer effects by attenuating the stemness STAT3 and NFkB pathways or mediates immune activating/modulatory effects by mitigating the same inflammatory factors STAT3 and NFkB in the tumor immune microenvironment (TIME)." (PMID 38539487, 2024). "Collectively, IL-22 could contribute to sorafenib resistance in HCC by activating STAT3/CD155 signaling axis to decrease the sensitivities of tumor cells to sorafenib-mediated direct cytotoxicity and NK cell-mediated lysis." (PMID 38596684, 2024). "Targeting STAT3 not only disrupts this chemoresistance mechanism but also reduces growth and clonogenicity in tumor-derived organoid models, emphasizing the potential of inhibiting this pathway to overcome Treg-mediated chemoresistance in tumor settings." (PMID 39461979, 2024). "Aberrant expression of IL-6 could promote tumor cell growth and metastasis by activating the IL-6/STAT3 signaling pathway." (PMID 38881895, 2024). "High expression of STAT3 in neutrophils attenuates their tumor-killing activities." (PMID 38245798, 2024). "Thus, the process of tumorigenesis can be influenced by purinergic activity, as the purinergic pathway leads to the activation of transcriptional factors involved with tumor growth (NF-kappa β and STAT3)." (PMID 39456655, 2024). "Studies have demonstrated that the bioactive compounds in TCM, such as saponins, terpenes, alkaloids and flavonoids, can down-regulate PD-L1 expression through various signaling pathways such as PI3K/Akt/mTOR, P38, NF-κB and JAK/STAT3, among others, thereby intervening in tumor immune escape." (PMID 38792234, 2024). "The inhibition to STAT3 significantly impaired fibroblast-induced tumor invasion in vitro." (PMID 38320998, 2024). "STAT3 is also known to promote tumor cell proliferation, survival, and invasion in diverse cancers." (PMID 39618825, 2024). "STAT3 is considered a potential subtarget for tumor therapy." (PMID 38172648, 2024). "To assess the translational significance of STAT3-MUC1 interactions in epithelial cancers, we analyzed tumor data from The Cancer Genome Atlas (TCGA) and found that STAT3 was significantly overexpressed in majority of epithelial cancers vs normal and correlated with worse survival outcomes." (PMID 38326371, 2024). "The abnormal activation of STAT3 promotes tumour proliferation, angiogenesis, and immune escape." (PMID 38455766, 2024).
tumor (continued). "Moreover, nuclear Pkm2 was reported to phosphorylate Stat3 at Y705 site to activate transcription, which is necessary for tumor transformation and progression." (PMID 39160208, 2024). "STAT3 is involved in tumor proliferation, invasiveness, angiogenesis, and migration." (PMID 39337272, 2024). "Other studies implicate c-JUN and STAT3 in tumor suppressive functions, too." (PMID 39358322, 2024). "The authors speculate that the upregulation of STAT3 may mediate the anti-tumor effects of dual HDAC/EGFR inhibition through a tumor-suppressive role, as opposed to its dual action as an oncoprotein." (PMID 38183103, 2024). "The JAK/STAT3 signaling pathway exhibits extensive overactivation in both inflammation and tumor." (PMID 39309424, 2024). "In addition, while higher p27pTpT increases sphere formation in 1833 cells, treatment with two siSTAT3, and STAT3 inhibition all impair the p27pTpT-mediated increase in tumor spheres." (PMID 38886396, 2024). "STAT3-YAP/TAZ signaling also plays a critical role in endothelial cells during tumor angiogenesis." (PMID 39738726, 2024). "We therefore suggest that the activation of MET- or STAT3-mediated signaling processes or those related to stress/senescence or inflammation strongly depends on the composition of the tumor microenvironment, likely determining the response to therapeutic interventions." (PMID 38386085, 2024). "Additionally, mRNA levels of interleukin-6 and tumor necrosis factor-alpha and active forms of signal transducer and activator of transcription 3 and nuclear factor-kappa B p65 were significantly increased in the tumor tissues of VDUP1 KO mice." (PMID 39272794, 2024). "Moreover, in addition to tumor suppression, the combination therapy of TP-0903 and WIN55212-2 induced the infiltration of cytotoxic CD8+ T cells and significantly reduced mTOR and STAT3 activation in tumor tissues of C57BL/6J mice bearing MC-38 cells." (PMID 39598377, 2024). "However, in the context of KRAS mutant NSCLC, compelling evidence suggests that STAT3 is a potent tumor suppressor." (PMID 38339245, 2024). "Mechanistic investigation demonstrated that FXR specifically bound to the promoters of IL-6ST and IL-6 genes to upregulate their transcription, thereby leading to activation of the Jak2/STAT3 signaling pathway, which facilitated tumor migration, invasion, and angiogenesis in NSCLC." (PMID 38360812, 2024). "Thus, the inhibition of the STAT3 pathway by lycorine in tumor cells can lead to various effects, including inducing apoptosis and suppressing migration and invasion." (PMID 39245716, 2024). "Additionally, STAT3 has been observed to increase production of PDL1 on tumour cells and can crosstalk with NFκB to enhance proliferation and resistance to apoptosis in tumour cells." (PMID 38623751, 2024). "In addition, NE can also act on tumor cells, modulating the STAT3 signaling pathway, which impacts tumor angiogenesis." (PMID 38567163, 2024). "Furthermore, the expression levels of IL-6R, STAT3, PD-L1, and VEGF-A, key molecules associated with tumor formation, were examined in the treated CT-26 cells to study the effects on tumor proliferation." (PMID 38725047, 2024). "Activated STAT3 RAs cells could therefore act by reducing the tumor infiltrate and creating an immunosuppressive microenvironment." (PMID 38781107, 2024). "The mtSTAT3 opens a new area of STAT3 tumor-promoting roles in cancer research." (PMID 38245798, 2024). "Studies linking STAT3 to the Hippo pathway suggest that the peritumoral STAT3 activation could be associated with Hippo pathway activation, leading to HLJ1-mediated tumor progression." (PMID 39738726, 2024). "Furthermore, inhibiting the interaction between STAT3 and Myc decreases the expression of the PD-L1 protein on tumor surfaces." (PMID 39660124, 2024). "Results of this study demonstrated that even partial downregulation of STAT3 in activated B cell-like DLBCL could suppress tumor growth." (PMID 39528914, 2024).
tumor (continued). "In addition to regulating the differentiation of Th17 and M2 macrophages, can STAT3 affect the differentiation of other tumor-related immune cells and have a more profound impact on the tumor microenvironment?" (PMID 38172648, 2024). "Collectively, RNF122 enhances tumor development through JAK2/STAT3/c‐Myc signaling axis activation." (PMID 39218810, 2024). "Additionally, the IHC assay suggested a significant reduction in p-STAT3 protein levels in the nude mice tumor tissues receiving usenamine A treatment." (PMID 38183094, 2024). "Indeed, the inactivation of STAT3 and STAT6 transcriptional factors is associated with reducing tumor growth and metastasis in a model of breast and lung cancer." (PMID 38542388, 2024). "One study showed that RNAi-mediated silencing of STAT3 and PD-L1 led to tumor growth inhibition by activating tumor-infiltrating immune cells, while RNAi-mediated silencing of STAT3/PD-L1 in tumor-associated immune cells induces robust antitumor effects in immunotherapy resistant tumors." (PMID 39618825, 2024). "SOCS3/phosphorylated JAK2/phosphorylated STAT3 could suppress DCs-mediated anti-tumour T cell responses, while silencing IL-23R-STAT3 or activating STAT5 could maintain TFR cell stability." (PMID 38581063, 2024). "Additionally, dinaciclib affects different cell growth regulators like EGFR and STAT3 on gene and protein level, thus decreasing tumor growth." (PMID 39668430, 2024). "In ESCC, advanced analyses integrating single-cell transcriptomic sequencing with bulk microarray data have uncovered that CCL18, released by TAMs, drives tumor cell proliferation via the JAK2/STAT3 signaling pathway, correlating with a poorer prognosis in ESCC." (PMID 39286635, 2024). "Research has shown that cross talk between TAMs and tumor cells can regulate the induction of the pluripotent gene SOX-2 through EGF receptor-mediated STAT3 signaling activation, and plays a crucial role in the expansion of cancer stem cells, chemotherapy resistance, and immune exclusion." (PMID 38693304, 2024). "Although a series of studies have shown that STAT3 is an ideal target for cancer therapy, at present, effective therapeutic interventions to inhibit STAT3 and produce powerful anti-tumor effects in the clinical environment need to be further explored and developed." (PMID 38320998, 2024). "Additionally, TGF-β, IL-6, and IL-8 released by CAFs and TAM can promote CSCs self-renewal and tumor progression by activating pathways like STAT3, NF-κB, and Wnt." (PMID 39611156, 2024). "Cycles of IL-6R/STAT3 signaling may promote metastatic spread by increasing the likelihood of favorable phenotypes detaching from the primary tumor and surviving long enough to colonize distant tissues." (PMID 38141171, 2024). "Additionally, PG regulates the expression of PD-1 on the surface of CD8+ T cells by reducing the secretion of VEGF-A in tumor cells, which is regulated by the levels of phosphorylated signal transducer and activator of transcription 3 (P-STAT3)." (PMID 38420194, 2024). "The abnormally activated IL-6/JAK2/STAT3 signaling pathway can contribute to the onset and progression of malignant tumors by affecting the proliferation, migration, invasion, angiogenesis, and apoptosis of tumor cells." (PMID 38881895, 2024). "There is emerging evidence that tumour derived IL-1β drives the IL-6/STAT3 axis and thus may act as a master cytokine to increase other transcription factors." (PMID 39516433, 2024). "However, persistent activation of the JAK2/STAT3 pathway has been associated with immune ICI resistance and tumor progression." (PMID 38974233, 2024). "Furthermore, PF-02341066 was an ALK inhibitor that can induce autophagy in various tumor cell lines by inhibiting the STAT3 pathway." (PMID 38506898, 2024).
tumor (continued). "Indeed, NSCLC cells expressing the STAT3 mutant which R609 was replaced to alanine (R609K) show significantly impaired tumour growth in nude mice." (PMID 38760429, 2024). "Indeed, this is reminiscent of the conversion of the canonical WNT and STAT3 signaling pathways in the context of mutant APC-driven tumor formation in the colonic mucosa." (PMID 39128004, 2024). "Similarly, IL-6/JAK/STAT3 signaling pathway potently activates inflammatory response via tumor-infiltrating immune cells in the tumor immune microenvironment in CRC." (PMID 37507626, 2024). "Moreover, Sunitinib exhibits immunomodulatory effects in tumor-bearing animals by targeting STAT3 and inhibiting PD-L1 expression specifically in OS." (PMID 39431237, 2024). "However, recent studies identified an alternative role for STAT3 as a tumor suppressor in a process dependent on the oncogenic environment and alternative splicing into the STAT3α and STAT3β isoforms." (PMID 38339245, 2024). "In TNBC, suppression of STAT3 expression inhibited tumor proliferation and migration." (PMID 38734640, 2024). "In addition, RIG-I reduces the proliferation of CRC tumor cells by inhibiting the STAT3 signaling pathway." (PMID 39867908, 2024). "Indeed, PAI-1-induced STAT3 activation plays a vital role in promoting tumor progression by enabling pro-tumorigenic polarization of TAMs, inducing epithelial–mesenchymal transition in cancer and promoting peritoneal carcinomatosis." (PMID 38779680, 2024). "Inhibition of STAT3 is a critical step in the control of tumor development and progression." (PMID 38474604, 2024). "Indeed, targeted‐muscle STAT3 signalling suppression protected against atrophy in tumour‐bearing mice." (PMID 38572511, 2024). "Furthermore, 1G11 inhibited LIF-induced p-STAT3 in vitro, and reduced p-STAT3 levels in tumor cells in tumor-bearing mice, thereby inhibiting tumor growth." (PMID 39169307, 2024). "We also found that circUBA2 could upregulate STC1 expression via miR-144-5p sponging and further activates the IL-6/JAK2/STAT3 signaling pathway, thereby promoting stemness and tumour progression in GC in vivo and in vitro." (PMID 39103836, 2024). "For example, TG2 mediates NF-κB activation, interleukin-6 (IL-6) upregulation, and Janus kinase/ signal transducer and activator of transcription 3 (JAK/STAT3) induction, thus promoting tumor progression, the acquisition of a stem-like phenotype, and neratinib resistance." (PMID 38474044, 2024). "However, when miR-9 and miR-218 downregulated the expression of IL-6 and Janus kinase 2 (JAK2), they inhibited the activation of STAT3, leading to the downregulation of STAT3 expression and thus inhibiting the growth of tumor cells." (PMID 38172648, 2024). "In addition to its intrinsic pro-tumoral roles, STAT3 mediates immune suppression in the tumor microenvironment." (PMID 39200368, 2024). "Moreover, the activities of AKT and STAT3 were repressed in both tumor cells and fibroblasts, and the EMT process in HNSCC was also reversed according to the staining of E-cadherin and N-cadherin." (PMID 38485986, 2024). "One of the effects of the release of IL-6 in the tumor is the activation of the STAT3 signaling pathway in malignant cells, altering cell-to-cell adhesions and promoting a number of cellular processes such as increased cell proliferation, enhanced motility and the activation of the EMT program." (PMID 38473317, 2024). "Given that HLJ1 may act as a tumor suppressor by dampening tumor growth through STAT3 activation inhibition, further research is essential to elucidate the complex crosstalk between peritumoral HLJ1/STAT3 signaling and liver tumors." (PMID 39738726, 2024). "Building upon these findings, our study provides further insights into the involvement of STAT3 in promoting lipid synthesis, thereby bolstering the evidence substantiating the modulation of lipid metabolism by STAT3 as a contributing factor to tumor cell growth." (PMID 38495496, 2024).